CD44 (CD44 molecule (IN blood group))
Diseases named in the same sentence as CD44 in open-access papers (continued):
Sharing a sentence is not in itself a finding about the gene and the disease.
breast carcinoma (continued). "Regarding gene CD44, as far as we know, its methylation status has not been reported in mammary tissue before, even though new evidence suggests its methylation in the breast cancer cell line MCF7." (PMID 22011321, 2011). "In previous studies, breast cancer cells cultured as mammospheres in serum-free medium are recognized as a CIC enriched subset and show enhanced radiation resistance and increased percentage of CD44+/CD24−or low cells." (PMID 21935375, 2011). "Our studies confirmed that SP cells sorted by flow cytometry from human breast cancer cell line MCF-7 showed high expression of CD44+CD24- cells and had greater tumorigenicity than non-SP and unsorted cells, which indicates SP cells enrich CSCs." (PMID 22032476, 2011). "A higher proportion of CD44+/CD24− tumour cells and ALDH1 positivity in pre-chemotherapy tissue was correlated with higher histologic grade, oestrogen receptor (ER) negativity, high Ki-67 proliferation index and basal-like subtype of breast cancer." (PMID 21559013, 2011). "Creighton and colleagues reported in 2009 that a gene expression signature common to both CD44+/CD24−/low and mammosphere-forming cells was found mainly in human breast cancer of the recently identified claudin-low molecular subtype, which is characterized by expression of many EMT-associated genes." (PMID 21253528, 2011). "This may be because the MCF-7 breast cancer cell line has a large population of cells which have stem cell-like properties and express ALDH1 and CD44." (PMID 22046561, 2011). "CD44+/CD24- and CD133 have been reported as TIC markers for breast cancer." (PMID 20727204, 2010). "Using a panel of 16 cancer lines we found that all breast cancer cell lines contained a population of CD44+ cells regardless of tumor subtype." (PMID 20964822, 2010). "Unlike M13SV1R2 cells, these R2d cells contain CD44+/CD24- cells previously identified as breast cancer stem cells and were responsive to estrogen for cell growth and tumor development." (PMID 21044318, 2010). "Thus, what are the potentially important differences between invasive and non-invasive breast cancer cells, and are the differences related to EMT or CD44/CD24 expression?" (PMID 20696077, 2010). "Both CD44+/CD24- and CD133 have been used as TIC markers for breast cancer and other malignancies." (PMID 20727204, 2010). "We studied the mechanisms of innate immunity to oncolytic adenovirus Ad5/3-Delta24 in conventional treatment resistant non-CIC breast cancer cells, breast cancer CD44+/CD24−/low CIC population and normal breast tissue CD44+/CD24−/low stem cells." (PMID 21079774, 2010). "The aim of the current study was to analyze the involvement of methyl-CpG binding proteins (MBDs) and histone modifications on the regulation of CD44, Cyclin D2, GLIPR1 and PTEN in different cellular contexts such as the prostate cancer cells DU145 and LNCaP, and the breast cancer cells MCF-7." (PMID 20565761, 2010). "During our analysis of breast cancer cell lines for subpopulations with the CD44+/CD24- phenotype, we observed that almost all cell lines with a CD44+/CD24- subpopulation were basal breast cancer cells that had undergone epithelial to mesenchymal transition (EMT)." (PMID 20691079, 2010). "Actively growing CD24-/low/CD44+ non-adherent mammospheres were isolated from monolayer cultures of MCF-7 breast cancer cells according to published procedures, with some minor modifications." (PMID 20525204, 2010). "Two gene-expression profiling studies, comparing CD24−/low/CD44+ cell populations with other populations in primary breast cancer cells or in normal tissue, presented the CD24−/low/CD44+ cell population-derived different signatures that seemed to predict poorer prognosis." (PMID 19997106, 2010).
breast carcinoma (continued). "Subsequent studies in solid tumours revealed that CD44+/CD24− and CD133+ sub-populations contained CSC populations in breast cancer and glioblastoma, respectively whereas more recent evidence of their existence has been demonstrated in melanoma, prostate, pancreatic, and colon cancer." (PMID 20332776, 2010). "In breast cancer, the CIC population has been shown to lie in the CD44+/CD24−/low portion." (PMID 21079774, 2010). "Clinically, basal-like breast cancer is characterized as the triple-negative phenotype (ER, PR, HER2, all negative) and as resembling stem-like cells, composed mainly of cells expressing the cancer stem cell markers CD44+ and cytokeratin 5/6." (PMID 19589136, 2009). "For example, both CD44+/CD24− and CD133+ cell populations had been identified from the same cancer in a BRCA breast cancer model, suggesting that one initial mechanism may lead to diverse CSCs with different phenotypes." (PMID 19568241, 2009). "It has also been shown that single cell suspensions of CD44+CD24−/lowLin− cells from human breast cancers were able to proliferate extensively and form clonal nonadherent mammospheres in a low attachment in vitro culture system." (PMID 20027313, 2009). "The potential existence of a stem cell-like cell in breast cancer was shown by Al-Hajj and colleagues, who identified a putative breast tumor stem cell-like population that is defined by the presence of CD44 and absence of CD24." (PMID 19589136, 2009). "Basal-B lines predominantly express CD44+/CD24−/low and MUC−/CALLA+ phenotypes characteristic of stem or bipotent progenitor cells, as well as ITGB3 (CD61), also recently characterized as a cancer stem cell marker in MMTV-wnt-1 induced murine breast cancer." (PMID 19582160, 2009). "Interestingly, inhibition of breast cancer stem cells by TGF-β1 was reported recently and TGF-β1 signalling is functional in CD44+ breast cancer cells." (PMID 19240712, 2009). "A correlation of the CD44+/CD24-/low phenotype to specific breast cancer subtypes has not yet been reported in human breast tumors." (PMID 18559090, 2008). "Collectively, these data suggest that, analogous to primary breast cancers, a basal cellular phenotype rather than tumorigenicity consistently correlates with the percentage of CD44+/CD24- cells in cell lines." (PMID 18366788, 2008). "In our studies, the cell lines derived from the original 0_A1 mammary tumor, but not cell lines from posterior tumors contained a population of CD44+/CD24-/low cells." (PMID 18394172, 2008). "Cell lines derived from individual Brca1 mouse mammary tumors had distinct and non-overlapping populations of putative cancer stem cell markers CD44+/CD24- and CD133+." (PMID 18241344, 2008). "To test the hypothesis that human breast cancer cell lines differ in the proportion of CD44+/CD24- cells, we characterized 13 breast cancer cell lines by flow cytometry for surface expression of CD44 and CD24." (PMID 17062128, 2006). "Moreover, diallyl trisulfide (DATS) suppresses the activity of breast cancer stem cells by the down-regulation of stemness markers (Nanog, Oct4, ALDH1, CD44), increased apoptosis (up-regulation of Bax protein, caspase-8, caspase-9, caspase-3), and the inhibition of Wnt/β-catenin signaling pathways." (PMID 39859345, 2025). "Similarly, other conventional stem cell markers such as CD133-, CD44-, CD49f-, and ALDH-expressing stem cells regulate various signaling networks, including the Notch, Hedgehog, and Wnt pathways, for maintenance and proliferation in breast cancer." (PMID 39858015, 2025). "GRP78 also colocalized with CD44 on the surface of breast cancer patient-derived circulating tumor cells, and superresolution dual-color single particle tracking further revealed dynamic interaction and coconfinement of GRP78 and CD44 in the plasma membrane nanodomains of breast cancer cells." (PMID 40699920, 2025).
breast carcinoma (continued). "The number of integrin β4+ CTCs expressing CD133 and ALDH1A1 stem markers but not CD44+CD24- was increased in metastatic breast cancer as well as in molecular subtypes of breast cancer with poor prognosis (luminal (HER2+) and TNBC) compared with luminal A/B (HER2−) subtype." (PMID 38250718, 2024). "Furthermore, exposure of tbLCM or loss of function of DACH1 in breast cancer cells significantly increased expression of KLF4, CD44 and Vimentin, indicating that one or more secreted factors in the LCM derived from TNBC tumor-bearing mice influences stemness/plasticity in breast cancer cells." (PMID 38581619, 2024). "Interestingly, studies have demonstrated that adding B27 to the culture media in non-adherent conditions improves tumoursphere formation efficiency and enhances the enrichment of the CD44 + /CD24–/low lineage, which can reach up to approximately 95% in breast cancer cell lines." (PMID 39003349, 2024). "In this work, with the aim to combine the CD44-targeting ability of HA and the redox-responsivity of cystamine (cys), we develop a nanoparticle system (FNPs) via ionic complexation at physiological pH of cysHSA derivative and HA for doxorubicin (DOX) vectorization in breast cancer cell lines." (PMID 39408889, 2024). "Although there has been a negative association between circulating anti‐CD44 antibodies and antigen in patients with specific malignant tumors, CD44 antigen exhibited a substantial negative link with the matching antibody in breast cancer patients in our current investigation." (PMID 36289579, 2023). "TNF-α treatment could switch the non-CSC (CD44+/CD24+) population to a CSC-like (CD44+/CD24−) population by increasing the expression of EMT factors in breast cancer cells." (PMID 36979874, 2023). "In addition, miR-138-5p was highly expressed in the MCF-7,but not in MCF-7/Adr, Skbr-3, and MDAMB-231 cell lines, suggesting a possible negative correlation between miR-138-5p and CD44 expression in breast cancer cells." (PMID 36964570, 2023). "CD44+CD24− cell populations have been found to have the greatest tumor-initiating potential in breast cancer and have been used, either alone or in combination with other markers (CD133, EpCAM, CD49f, CD90, and CD61), to identify and isolate breast cancer stem cells (BCSCs)." (PMID 36979915, 2023). "CD44 ICD can also interact with CREB to bind to the gene promoter region of PFKFB4, a key enzyme of glycolysis, to regulate the transcription and expression of PFKFB4, thereby regulating breast cancer cell stemness and affecting breast cancer patient prognosis." (PMID 36964570, 2023). "Indeed, a high CD44/CD24 ratio and ALDH1+ expression were found invariable in primary tumors, CTCs, and distant metastases, suggesting their stability during the development and metastasis of breast cancer." (PMID 36594086, 2023). "In this model, the oligonucleotide-based therapeutic-treated cells were characterized by a decrease in CD44 and an increase in the amount of CD24 protein on the cell surface, which may be related to the differentiation of breast cancer cells related to losing stem-like phenotypes." (PMID 38067351, 2023). "Moreover, CD44 is not exclusively expressed in cancer stem cells (CSCs) but also in claudin-low breast cancer cell lines such as MDA-MB-231 and Hs578T." (PMID 36831218, 2023). "A significant upregulation of syndecan-1 and a positive correlation with the expression of CD44, a marker of cancer stem cell (CSC) phenotype, have been documented in inflammatory breast cancer, a particularly aggressive BC subtype." (PMID 36088392, 2023). "Interestingly, the classic breast cancer marker genes, BRCA1 and CD44 were overexpressed in the PABC PPI network, suggesting that PABC may be characterized by higher activity of proteins that contribute to NPABC." (PMID 36035177, 2022). "Hence, the CD44/PD-L1 axis could be a critical therapeutic target for treating TNBC and other breast cancer subtypes." (PMID 35053979, 2022).
breast carcinoma (continued). "Hierarchical tumor organization was also shown in solid cancers, as for instance only CD44+/CD24-/low tumorigenic breast cancer cells were able to form tumors that contained additional CD44+/CD24-/low cells, as well as phenotypically different non-tumorigenic cells." (PMID 35328833, 2022). "In vitro mammary spheroid formation, flow cytometry assay on CD24−/CD44+ sub-population, ALDH activity detection, cell viability assay and western blot analysis, and in vivo tumor-initiating analysis were performed to examine the effects of Tanshinone IIA on the stemness of breast cancer cells." (PMID 35057866, 2022). "Inhibition of WNT1 changes the phenotype of CD44+CD24−ALDH1 stem cells and reduces their ability to form tumours and cell migration, and suppression of GSK3/β-catenin signals by an inhibitor of protein kinase D1 (PRKD1) is sufficient to reduce the stem and chemoresistance of breast cancer cells." (PMID 35563449, 2022). "Furthermore, we showed that HIF-2α, but not HIF-1α, was highly expressed in CD44+CD24− breast cancer tissues." (PMID 35301432, 2022). "Our previous lncRNA microarray analysis identified that RBM5-AS1 (RBM5 antisense RNA 1) was upregulated in both BCSCs MCF-7 cells (CD44+CD24−) and poorly differentiated breast cancer tissues (high-grade) compared with non-BCSCs MCF-7 cells (non-CD44+CD24−) and paracancerous normal tissues." (PMID 35110544, 2022). "It has been reported that hyaluronan–CD44 interactions are capable of stimulating ABCB1 expression and activity through promoting ankyrin–cytoskeleton interactions, Nanog-Stat-3 signalling, ErbB2 signalling and PI3K/AKT-related survival pathways in breast cancer cell lines." (PMID 33801148, 2021). "Interestingly, another study argued that a high CD44/CD24 ratio was mainly in charge of cell proliferation and tumorigenesis in breast cancer, while the aldehyde dehydrogenase 1 (ALDH1)-positive phenotype was significantly associated with cell migration and metastasis." (PMID 33801148, 2021). "However, OSM-induced CD44 was shown to contribute to breast cancer metastatic potential through cell detachment but not EMP itself in another study." (PMID 34361105, 2021). "The proportion of CD44+CD24− cell subsets in the serum‐free suspension culture of MCF‐7‐CSC was significantly higher than that of MCF‐7 (P < 0.05), indicating that the presence of surface markers of breast cancer stem cells in MCF‐7‐CSC had increased significantly than that of in MCF‐7." (PMID 33305893, 2021). "CD44 is a cell surface adhesion molecule that mediates cell‐cell and cell‐extracellular matrix (ECM) interactions by binding to hyaluronic acid (HA), whilst CD24 is a small sugar involved in the negative regulation of chemokine receptor CXCR4 protein activity in mediating breast cancer metastasis." (PMID 33305893, 2021). "CD44+/CD24− has been widely used as BCSC surface markers, thus we sorted CD44+/CD24− subpopulation (termed as BCSCs) from various breast cancer cells and clinical tumor samples, and other remaining subpopulations (CD44+/CD24+, CD44−/CD24+, CD44−/CD24−) were termed as non-BCSCs." (PMID 33934099, 2021). "Therefore, it is evident that CD44 marks several cell states in normal breast and breast cancer tissues, including cells that have CSC and non-CSC roles." (PMID 34120626, 2021). "Studies show that CD44, a hyaluronic acid (HA) binding transmembrane glycoprotein, forms a complex with the nonintegral cell surface protein RHAMM to promote tumor cell migration, and both may be upregulated in breast cancer." (PMID 34338608, 2021). "The N-cadherin and CD44 had correlations with most SWE parameters, and also showed the best correlation with the anisotropy of different cross-sectional stiffness, indicating that the greater the stiffness of breast cancer, the greater the difference in the stiffness of the cross section." (PMID 34789199, 2021).
breast carcinoma (continued). "However, no guidelines currently exist for defining a CTC-CSC phenotype, although a common classification of CSCs of high CD44 and low CD24 expression (CD44+/CD24−/low), is frequently utilised in breast cancer, and breast tumours with this expression tend to exhibit enhanced invasion and metastasis." (PMID 33789677, 2021). "However, c10orf118 silencing modified the expression of HAS2 and its epigenetic regulator HAS2-AS1, as well as the levels of the HA receptor CD44, suggesting a specific effect on HA metabolizing genes rather than the behaviour of breast cancer cells." (PMID 33807583, 2021). "For examples, in osteosarcoma, colorectal cancer, liver cancer and breast cancer, miR-328-3p overexpression inhibited their migration, invasion, and EMT by directly inhibiting MMP-16, Girdin, Endoplasmic Reticulum Metallo Protease 1 (ERMP1) and CD44, respectively 17, 26-29." (PMID 34659543, 2021). "The co-expression of CD44 and CD47 in tumor cells may contribute to breast cancer metastasis." (PMID 34205080, 2021). "A recent study reported a significant increase in the percentage of CD44+/CD24–/low breast CSCs in biopsies specimens following chemotherapy, suggesting that modulating Notch in breast cancers may be a promising strategy to reduce drug resistance by eliminating the CSC subpopulation." (PMID 33681228, 2021). "At the marker profile, the Quiescent stem-like population expresses the pluripotency markers, while the Progenitor population in breast cancer cells can be marked by CD44 with diminished pluripotency markers and without other CSC markers like ALDH1A1/3 or ABCG2." (PMID 34150761, 2021). "In breast cancer cells, IGF2BP3 has a direct correlation with E-cadherin, vimentin, and Slug (P < 0.05) and further promotes invasion and migration by prompting the EMT83 and reducing cell apoptosis by activating the Hedgehog signalling pathway CD44/CD44+Fbs/IGF2." (PMID 34044876, 2021). "The results indicated that CD44 was detected in TNBC cells, such as MDA-MB-231, derived from a metastatic site of human breast cancer compared to the HER2+ breast cancer cells, except for the AU-565 cell line, which was isolated from a metastatic site of human breast cancer." (PMID 34770956, 2021). "Furthermore, miR-7 overexpression could suppress the tumorigenicity of CD44+CD24−ESA+BCSCs and reduce the BCSC subset in breast cancer animal model." (PMID 32143670, 2020). "Moreover, the tumorigenic CD44+/CD24neg/low side population of BCSCs derived from MCF7 and MDA-MB-231 breast cancer cells showed greater MSFE and were resistant to radiation when compared to the parental MCF7 and MDA-MB-231 breast cancer cells." (PMID 32883003, 2020). "Moreover, miR-7 suppressed CD44 and ESA by directly inhibiting the NF-κB subunit RELA and slug in breast cancer cell lines and in BCSC-driven xenografts, which confirmed the antitumor activity in mice injected with miR-7 agomir or stably infected with lenti-miR-7." (PMID 32143670, 2020). "Likewise, even though more than 90% of basal-like breast cancer cell lines were CD44+/CD24−/low this phenotype was not correlated with tumorigenicity." (PMID 32430004, 2020). "Considering the conflicting nature of data regarding BCSC phenotypes, it is important to systematically investigate the expression of CD44, CD24 and ALDH1A1 in different breast cancer subtypes to understand whether the expression of these biomarkers indeed correlates with tumorigenic potential." (PMID 32423137, 2020). "Prepared HA-QDs showed enhanced stability in PBS and fluorescence stability, and excellent targeting ability to CD44+ breast cancer cells without cytotoxicity, indicating that the stability and low-toxicity of QDs could be achieved through an HA coating." (PMID 32290285, 2020).